SDCBP (syndecan binding protein)
Description:
Multifunctional adapter protein involved in diverse array of functions including trafficking of transmembrane proteins, neuro and immunomodulation, exosome biogenesis, and tumorigenesis. Positively regulates TGFB1-mediated SMAD2/3 activation and TGFB1-induced epithelial-to-mesenchymal transition (EMT) and cell migration in various cell types. May increase TGFB1 signaling by enhancing cell-surface expression of TGFR1 by preventing the interaction between TGFR1 and CAV1 and subsequent CAV1-dependent internalization and degradation of TGFR1. In concert with SDC1/4 and PDCD6IP, regulates exosome biogenesis. Regulates migration, growth, proliferation, and cell cycle progression in a variety of cancer types. In adherens junctions may function to couple syndecans to cytoskeletal proteins or signaling components. Seems to couple transcription factor SOX4 to the IL-5 receptor (IL5RA). May also play a role in vesicular trafficking. Seems to be required for the targeting of TGFA to the cell surface in the early secretory pathway.
Synonyms: MDA-9; TACIP18; MDA9; SYCL; SDCBP1; ST1
Tractability: Small molecule: a structure with a bound ligand is known; a high-quality ligand is known; it has a binding pocket of medium quality. Antibody: UniProt places it where antibodies can reach, with high confidence; its Gene Ontology location is reachable by antibodies, with high confidence. PROTAC: ubiquitination databases record sites on it; its protein half-life has been measured; a small molecule that binds it is known.
Gene: Protein-coding gene on chromosome 8 (58,552,924 to 58,583,800, forward strand). Ensembl gene ENSG00000137575.
Subcellular location: Cell junction, focal adhesion; Cell junction, adherens junction; Cell membrane; Endoplasmic reticulum membrane; Nucleus; Melanosome; Cytoplasm, cytosol; Cytoplasm, cytoskeleton; Secreted, extracellular exosome; Membrane raft
Subcellular location (Human Protein Atlas): Cytosol; Nucleoplasm; Nuclear membrane
Pathways (Reactome):
Developmental Biology: Ephrin signaling; Neurofascin interactions
Programmed Cell Death: RIPK1-mediated regulated necrosis; Regulation of necroptotic cell death
Immune System: Neutrophil degranulation
Gene Ontology:
Molecular function: frizzled binding; identical protein binding; phosphatidylinositol-4,5-bisphosphate binding; protein binding; protein heterodimerization activity; protein sequestering activity; syndecan binding; cytoskeletal anchor activity; interleukin-5 receptor binding
Biological process: negative regulation of receptor internalization; negative regulation of transcription by RNA polymerase II; positive regulation of cell growth; positive regulation of cell migration; positive regulation of cell population proliferation; positive regulation of epithelial to mesenchymal transition; positive regulation of exosomal secretion; positive regulation of extracellular exosome assembly; positive regulation of phosphorylation; positive regulation of transforming growth factor beta receptor signaling pathway; regulation of mitotic cell cycle; actin cytoskeleton organization; chemical synaptic transmission; intracellular signal transduction; positive regulation of JNK cascade; protein targeting to membrane; substrate-dependent cell migration, cell extension
Cellular component: blood microparticle; cytoplasm; cytosol; endoplasmic reticulum membrane; extracellular exosome; extracellular region; extracellular vesicle; melanosome; membrane raft; nuclear membrane; nucleoplasm; plasma membrane; adherens junction; azurophil granule lumen; cytoskeleton; interleukin-5 receptor complex; membrane; nucleus; focal adhesion; synapse
Genetic constraint (gnomAD): Loss-of-function variants: 6 observed, 10.86 expected, observed/expected ratio (o/e) 0.55, 90% interval 0.3 to 1.09. The upper end of that interval is the gene's LOEUF score, 1.09, which puts it in group 4 of 6, group 1 being the genes least tolerant of losing a copy. Missense variants: 167 observed, 199.77 expected, observed/expected ratio (o/e) 0.84, 90% interval 0.74 to 0.95. Synonymous variants: 47 observed, 64.02 expected, observed/expected ratio (o/e) 0.73, 90% interval 0.58 to 0.94.
Homologues: Orthologues: chimpanzee SDCBP (95% identical), dog SDCBP (95% identical), guinea pig SDCBP (94% identical), macaque SDCBP (94% identical), mouse Sdcbp (90% identical), rat Sdcbp (90% identical), pig SDCBP (89% identical), rabbit SDCBP (89% identical), tropical clawed frog sdcbp (78% identical), Caenorhabditis elegans lin-10 (23% identical), Drosophila melanogaster X11Lbeta (23% identical). Paralogues in human: SDCBP2 (57% identical), APBA1 (29% identical), APBA2 (27% identical), APBA3 (25% identical).
Diseases named in the same sentence as SDCBP in open-access papers:
SDCBP is named in the same sentence as 72 diseases in open-access papers, as found by Europe PMC text mining. Sharing a sentence is not in itself a finding about the gene and the disease. The quoted sentences say what the papers report.
melanoma (28 papers, 2012 to 2025). A malignant, usually aggressive tumor composed of atypical, neoplastic melanocytes. "Since its discovery, SDCBP was implicated in melanoma metastasis and associated with multiple cellular functions, including cell-cell interactions, cell-matrix adhesion, signal transduction, and cell trafficking." (PMID 34638436, 2021). "Syntenin (also known as syndecan-binding protein, SDCBP) was initially cloned from terminally differentiating human melanoma cells as melanoma differentiation-associated gene-9 (MDA-9)." (PMID 28418925, 2017). "A comparative proteomic analysis revealed syntenin-1, also known as syndecan-binding protein (SDCBP) or melanoma differentiation-associated gene-9 (MDA-9), to be one of the proteins most highly overexpressed in CCL-138-R cells and CSCs compared to CCL-138 cells." (PMID 34638436, 2021). "miR-23a reduces syntenin-1 expression by binding to SDCBP, thereby inhibiting the progression and migration of melanoma cells through MAPK/ERK pathway inhibition." (PMID 37298370, 2023). "SDCBP also regulates cell membrane motility and promoted tumor growth and metastasis in melanoma, prostate, breast and gastric cancer cells." (PMID 35241737, 2022). "Syntenin was originally identified from metastatic human melanoma, also known as melanoma differentiation-associated gene-9 (MDA-9) and syndecan-binding protein (SDCBP)." (PMID 35756080, 2022). "The role of SDCBP as an EMT inducer in breast cancer and melanoma has been associated with small GTPases and Slug, respectively." (PMID 34638436, 2021). "Conversely, it was suggested that SDCBP binds to Src in melanoma, resulting in its activation (p-Src) and downstream signaling." (PMID 34638436, 2021). "Syntenin-1 (syndecan-binding protein, SDCBP), also known as melanoma differentiation-associated gene-9 (MDA9), participates in the induction of the EMT process by positively regulating Smad activation, mediated by TGF-β1." (PMID 33506060, 2021). "Melanoma differentiation associated gene-9 (mda-9, also known as Syntenin-1, SDCBP), a gene first cloned by our group, is robustly expressed in multiple cancers including melanoma and contributes to invasion and metastasis in a tumor cell-intrinsic manner." (PMID 27341128, 2016). "The SDCBP gene encodes a PDZ domain-containing protein, involved in exosome biogenesis and Rho GTPase family regulation, and participates in NF-KB activation in melanoma." (PMID 33833385, 2021). "Studies have suggested that SDCBP, also known as “Melanoma differentiation-associated gene-9” (MDA-9), participates in invasion and metastasis in several cancers, albeit mainly in melanomas." (PMID 34445387, 2021). "The role of SDCBP in the melanoma metastasis has been extensively studied." (PMID 23533663, 2013). "Syndecan binding protein (SDCBP), an adapter protein containing PDZ domains, contributes to the tumorigenicity and metastasis of many malignant tumors, such as malignant melanoma." (PMID 23533663, 2013).
breast carcinoma (25 papers, 2007 to 2025). "SDCBP is also suggested as a tumor biomarker as well as a promising therapeutic target in breast cancer treatments." (PMID 40263598, 2025). "Previous studies reported that the PDZ1 inhibitor (PDZ1i) of SDCBP inhibited the invasion of glioblastoma and breast cancer cells." (PMID 37460462, 2023). "The same study provides clinical evidence that the miR-135b-5p/SDCBP axis plays a crucial role in the metastasis of early-stage breast cancer." (PMID 36980680, 2023). "SDCBP is negatively correlated with ER in breast cancers and is down regulated by estrogen treatment." (PMID 31895944, 2020). "Collectively, this study presents novel evidence suggesting that TMEM68, IMPAD1, SDCBP, and RBM12B are potential modifiers of human breast cancer risk and outcome." (PMID 30914425, 2019). "MDA-9/syntenin (SDCBP) expression is elevated in breast cancer patient samples as well as cultured breast cancer cells." (PMID 27863394, 2016). "Our study aimed in revealing the expression profile of SDCBP in breast cancer (BCa) and its role in tumor cell proliferation, and then exploring its value in the targeted treatment of BCa." (PMID 23533663, 2013). "However, in early-stage breast cancer, miR-135b-5p repression resulted in migration through the syndecan-binding protein (SDCBP)." (PMID 35327452, 2022). "Moreover, miR-216b could inhibit cell growth and metastasis of breast cancer cells via decreasing syndecan-binding protein (SDCBP)." (PMID 34281530, 2021). "Western blot analyses showed high SDCBP and BACH1 protein expressions in TNBC cell lines (e.g., MDA-MB-231, MDA-MB-468, and Hs578T), while lower levels were found in luminal A breast cancer cell lines (e.g., MCF-7 and T47D) (Fig. EV1C,D)." (PMID 40263598, 2025). "An overexpression of miR-135b-5p retards breast cancer cell growth, the EMT, migration, invasion, and metastasis via the direct targeting of SDCBP in vitro and in breast tumor xenografts." (PMID 36980680, 2023). "For example, SDCBP was found to modulate RhoA and Cdc42 expression via TGF-β1, which induced EMT and promoted breast cancer metastasis." (PMID 35155233, 2022). "We then investigated SDCBP and BACH1 expression levels in several human breast cancer cell lines." (PMID 40263598, 2025). "Real-time quantitative polymerase chain reaction (qPCR) analyses revealed that the mRNA expression levels of SDCBP, but not those of BACH1, correlated with the protein expression levels in the breast cancer cell lines (Fig. EV1D,E)." (PMID 40263598, 2025).
glioma (18 papers, 2016 to 2025). A benign or malignant brain and spinal cord tumor that arises from glial cells (astrocytes, oligodendrocytes, ependymal cells). "In acid-resistant glioma stem cells, by regulating the SDCBP/MDA-9/syntenin-mediated protective autophagy signaling pathway, it is feasible to shift the intracellular homeostasis from pro-survival to pro-cell death." (PMID 37422448, 2023). "In contrast, glioma stem cells with silenced syndecan-binding protein reported higher levels of autophagy, which reduced anoikis resistance." (PMID 33526785, 2021). "In glioma tissues, syndecan-binding protein (SDCBP), which controls the proliferation and invasion of cancer cells, is positively correlated with IL-6 expression level, and IL-6 stimulation induces SDCBP expression at mRNA and protein levels in a dose- and time-dependent manner." (PMID 36591515, 2022). "Anoikis resistance also occurs via the regulation of SDCBP/MDA-9/Syntenin in gliomas." (PMID 35686268, 2022). "First, we confirmed that alisertib treatment increased B7-H3, SDCBP, and phosphorylated EGFR expression in glioma cells." (PMID 39928563, 2025).
lung carcinoma (7 papers, 2022 to 2024). "SDCBP upregulates Slug expression, thereby mediating suppression of E-cadherin to induce EMT in lung cancer." (PMID 35155233, 2022).
Autoimmunity (6 papers, 2018 to 2023). The occurrence of an immune reaction against the organism's own cells or tissues. "The p.Pro480Thr variant is predicted to affect the C-terminal tail of the UNC93B1 that has recently been shown to restrict TLR7 mediated autoimmunity via an interaction with syndecan binding protein (SDCBP)." (PMID 32028618, 2020).
glioblastoma (6 papers, 2016 to 2023). The most malignant astrocytic tumor (WHO grade IV). "In glioblastoma, miR-135a-5p and miR-124-3p interact with SDCBP to inhibit syntenin-1 expression, thereby obstructing growth, migration, and infiltration." (PMID 37298370, 2023). "Syntenin-1, a syndecan-binding protein, in fact appears to be co-expressed with EGFR and to regulate its signalling in both glioblastoma and urothelial cell carcinoma." (PMID 33302515, 2020).
prostate carcinoma (6 papers, 2019 to 2023). A carcinoma that arises from epithelial cells of the prostate gland. "Our results corroborate the role of SDCBP in CSCs, as reported in prostate cancer." (PMID 34638436, 2021). "Moreover, it has been demonstrated that PDZ1, an SDCBP target-specific small-molecule inhibitor, displays therapeutic potential for prostate cancer and potentially other cancers expressing elevated levels of SDCBP." (PMID 34445387, 2021). "By physically interacting with IGF-1R, SDCBP activates STAT3 and thus regulates prostate cancer pathogenesis." (PMID 34445387, 2021). "We now show that MDA-9/Syntenin/SDCBP (MDA-9) is a critical regulator of survival, stemness and chemoresistance in prostate cancer stem cells (PCSCs)." (PMID 31878027, 2019).
uveal melanoma (5 papers, 2012 to 2023). A melanoma derived from melanocytes of the uveal tract. "Interestingly, we observed that high expression of SDCBP is related to the class 2-gene signature, which has been associated with metastatic behavior of uveal melanoma." (PMID 22267972, 2012). "In the present work we find an elevated expression of SDCBP by gene expression profiling in a cohort of 29 primary uveal melanomas." (PMID 22267972, 2012). "To assess the possible role of mda-9/syntenin in uveal melanoma metastatic process we silenced SDCBP expression by siRNA in 92.1 and Mel 270 cells with siRNA and studied the effects on cell migration." (PMID 22267972, 2012). "In the search of possible molecular pathways involved in uveal melanoma progression we focused our attention on SDCBP gene, which we detected as a highly expressed gene through a microarray analysis." (PMID 22267972, 2012). "The inhibition of SDCBP expression by siRNA impaired the ability of uveal melanoma cells to migrate in a wound–healing assay." (PMID 22267972, 2012). "In the present study, a correlation of high SDCBP gene expression with metastatic progression was suggested by the analysis of the gene expression profile of 29 primary uveal melanomas." (PMID 22267972, 2012). "To further study the role of SDCBP in uveal melanoma metastases, we developed a pseudometastatic model obtained by intrasplenic injection of uveal melanoma cell lines." (PMID 22267972, 2012). "MEL 270 and 92.1 cell lines, which derive from primary tumors, and OMM1 and OMM2.5 deriving from skin and liver metastases, respectively clearly expressed SDCBP, thus confirming that SDCBP is expressed by uveal melanoma neoplastic cells." (PMID 22267972, 2012). "Moreover, a study has shown that inhibition of syndecan-binding protein syntenin-1 (SDCBP) expression by siRNA impaired the ability of uveal melanoma cells to migrate in a wound-healing assay." (PMID 33810567, 2021). "The correlation of SDCBP mRNA levels with recurrence was further confirmed by the analysis of the raw data of two previously reported datasets of 27 and 63 primary uveal melanomas, respectively." (PMID 22267972, 2012). "Moreover, silencing of SDCBP in mda-9/syntenin-high uveal melanoma cells inhibited the hepatocyte growth factor (HGF)-triggered invasion of matrigel membranes and inhibited the activation of FAK, AKT and Src." (PMID 22267972, 2012). "In conclusion, our present data indicate that SDCBP mRNA and mda-9/syntenin protein deserve further investigation as candidate prognostic markers of uveal melanoma and as potential targets for novel therapies aimed at blocking the metastatic process in this tumor." (PMID 22267972, 2012). "Moreover, we found that high expression of SDCBP gene was related to metastatic progression in two additional independent datasets of uveal melanoma patients." (PMID 22267972, 2012).
gastric cancer (4 papers, 2016 to 2023). A primary or metastatic malignant neoplasm involving the stomach. "Hsa-miR-361-5p was reported to exert tumor-suppressing functions in gastric carcinoma by targeting syndecan-binding protein." (PMID 34948403, 2021). "It inhibits syntenin-1 expression by binding with SDCBP, thereby promoting cancer growth and inhibiting apoptosis in gastric cancer." (PMID 37298370, 2023).
triple-negative breast carcinoma (3 papers, 2016 to 2025). An invasive breast carcinoma which is negative for expression of estrogen receptor (ER), progesterone receptor (PR), and human epidermal growth factor receptor 2 (HER2). "Adapter protein SDCBP stabilizes BACH1 in triple-negative breast cancer cells, thus regulating transcription of pro-metastatic and mitochondrial genes." (PMID 40263598, 2025). "Syndecan-binding protein (SDCBP) and tyrosine-419 phosphorylated c-src (p-c-src-Y419) expression and the pathological features of triple-negative breast cancers." (PMID 28141839, 2017). "This work identifies adapter protein syndecan-binding protein 1 (SDCBP, syntenin-1) as a BACH1 regulator in triple-negative breast cancer (TNBC) cells, controlling transcription of pro-metastatic and mitochondrial genes." (PMID 40263598, 2025).
urothelial cell carcinoma (3 papers, 2020 to 2024). "Notably, SDCBP interacts with EGFR in urothelial cell carcinoma and modulates EGFR signaling." (PMID 38649770, 2024).
esophageal squamous cell carcinoma (2 papers, 2024). Esophageal squamous cell carcinoma (ESCC) is a type of esophageal carcinoma (EC) that can affect any part of the esophagus, but is usually located in the upper or middle third. "SDCBP is frequently overexpressed in esophageal squamous cell carcinoma (ESCC) tissues as compared to controls, is strongly correlated with late clinical stage, and predicts poor prognosis in patients." (PMID 39334449, 2024). "Syndecan-binding protein (SDCBP) was reported to stimulate the advancement of esophageal squamous cell carcinoma (ESCC) and could potentially be a target for ESCC treatment." (PMID 38649770, 2024).
head and neck cancer (2 papers, 2021 to 2023). A primary or metastatic malignant neoplasm affecting the head and neck. "Overall, the experiments demonstrate that SDCBP is directly involved in the acquisition of resistance in primary and established head and neck cancer cell lines." (PMID 34638436, 2021).
lymph node metastasis (2 papers, 2016 to 2020). "The expression level of SDCBP was significantly increased in HNSC tissues compared to the adjacent normal tissues (P < 0.0001) and closely associated with lymph node metastasis (P = 0.0254)." (PMID 27811365, 2016).
non-small cell lung carcinoma (2 papers, 2023 to 2025). A group of at least three distinct histological types of lung cancer, including non-small cell squamous cell carcinoma, adenocarcinoma, and large cell carcinoma. "In non-small-cell lung cancer, a reduction in exosomal miR-1273a was found to induce CDDP resistance by increasing Syndecan-binding protein (SDCBP) levels in recipient cells." (PMID 37895415, 2023).